PYDC1 (pyrin domain containing 1)
Description:
Associates with PYCARD/ASC and modulates its ability to collaborate with MEFV/pyrin and NLRP3/cryopyrin in NF-kappa-B and pro-caspase-1 activation. Suppresses kinase activity of NF-kappa-B inhibitor kinase (IKK) complex, expression of NF-kappa-B inducible genes and inhibits NF-kappa-B activation by cytokines and LPS.
Synonyms: cPOP1; ASC2; POP1; PYC1
Tractability: No criterion of Open Targets' tractability assessment is met for any kind of drug.
Gene: Protein-coding gene on chromosome 16 (31,215,962 to 31,217,162, reverse strand). Ensembl gene ENSG00000169900.
Subcellular location: Cytoplasm
Gene Ontology:
Molecular function: protein binding; protein serine/threonine kinase binding; protein serine/threonine kinase inhibitor activity
Biological process: innate immune response; negative regulation of canonical NF-kappaB signal transduction; negative regulation of interleukin-1 beta production; negative regulation of interleukin-1-mediated signaling pathway; negative regulation of NLRP3 inflammasome complex assembly; negative regulation of tumor necrosis factor-mediated signaling pathway; positive regulation of interleukin-1 beta production; defense response; immune system process; regulation of tumor necrosis factor-mediated signaling pathway; response to other organism
Cellular component: cytosol; IkappaB kinase complex; nucleus; cytoplasm
Genetic constraint (gnomAD): Loss-of-function variants: 1 observed, 0.76 expected, observed/expected ratio (o/e) 1.32, 90% interval 0.3 to 1.91. That is too few expected variants to judge how well the gene tolerates losing a copy. Missense variants: 129 observed, 134.18 expected, observed/expected ratio (o/e) 0.96, 90% interval 0.83 to 1.11. Synonymous variants: 37 observed, 66.41 expected, observed/expected ratio (o/e) 0.56, 90% interval 0.43 to 0.73.
Homologues: Orthologues: chimpanzee PYDC1 (100% identical), macaque PYDC1 (90% identical), Caenorhabditis elegans ced-3 (15% identical), zebrafish casp20 (15% identical), zebrafish casp8 (15% identical), Caenorhabditis elegans csp-1 (13% identical), Caenorhabditis elegans csp-2 (13% identical), Drosophila melanogaster Dronc (13% identical), Drosophila melanogaster Decay (12% identical), tropical clawed frog casp8 (12% identical), tropical clawed frog XB5812047 (9% identical), zebrafish casp3l (3% identical), and 1 more. Paralogues in human: PYCARD (65% identical), CASP9 (22% identical), CFLAR (20% identical), CASP2 (18% identical), CASP8 (18% identical), CASP6 (17% identical), CASP12 (16% identical), CASP10 (15% identical), CASP5 (15% identical), CASP7 (15% identical), CASP4 (13% identical), CASP1 (11% identical), and 4 more.
Diseases named in the same sentence as PYDC1 in open-access papers:
PYDC1 is named in the same sentence as 8 diseases in open-access papers, as found by Europe PMC text mining. Sharing a sentence is not in itself a finding about the gene and the disease. The quoted sentences say what the papers report.
endometriosis (1 paper, 2024). The growth of functional endometrial tissue in anatomic sites outside the uterine body. "However, the potential association between single nucleotide polymorphisms (SNPs) of the NOD1, NOD2, PYDC1, and PYDC2 genes and the predisposition to endometriosis risk remains unexplored." (PMID 40034240, 2024).
ovarian endometriosis (1 paper, 2024). A non-neoplastic disorder characterized by the growth of endometrial tissue in the ovaries. "In this study, we aim to investigate inflammasome regulators PYDC1 and PYDC2 and genetic variations in the NOD1 and NOD2 genes in patients with ovarian endometriosis." (PMID 40034240, 2024).
psoriasis (1 paper, 2017). An autoimmune condition characterized by red, well-delineated plaques with silvery scales that are usually on the extensor surfaces and scalp. "Interestingly, a study of psoriasis-associated changes in the skin transcriptome showed upregulation of PYDC1 and PYCARD in psoriasis lesions." (PMID 29234126, 2017).
cancer (2 papers, 2022 to 2024). A tumor composed of atypical neoplastic, often pleomorphic cells that invade other tissues. "In contrast, several PRGs, such as TLR4 and PYDC1, showed miscellaneous cancer-type-specific patterns that have not been previously characterized." (PMID 35008400, 2022).
infection (2 papers, 2012 to 2025). The state of being infected such as from the introduction of a foreign agent such as serum, vaccine, antigenic substance or organism. "Although not statistically significant, the ISG PYDC1 was most upregulated by EBOVΔVP30 infection." (PMID 41472248, 2025).
PYDC1 also shares sentences with these, for which no sentence is quoted: listeriosis (2 papers); lactic acidosis (1); thymoma (1).